SYN3 (synapsin III)
Description:
May be involved in the regulation of neurotransmitter release and synaptogenesis.
Tractability: Small molecule: a structure with a bound ligand is known; it has a high-quality binding pocket. Antibody: UniProt places it where antibodies can reach, with medium confidence. PROTAC: its protein half-life has been measured.
Gene: Protein-coding gene on chromosome 22 (32,507,820 to 33,058,381, reverse strand). Ensembl gene ENSG00000185666.
Subcellular location: Cytoplasmic vesicle, secretory vesicle, synaptic vesicle membrane
Pathways (Reactome):
Neuronal System: Dopamine Neurotransmitter Release Cycle; Serotonin Neurotransmitter Release Cycle
Gene Ontology:
Molecular function: protein binding; ATP binding
Biological process: neurotransmitter secretion; regulation of synaptic transmission, GABAergic; synapse organization; synaptic vesicle clustering; chemical synaptic transmission; modulation of chemical synaptic transmission; synaptic vesicle cycle
Cellular component: synaptic vesicle; synaptic vesicle membrane; extrinsic component of synaptic vesicle membrane; glutamatergic synapse; postsynaptic density; synapse
Genetic constraint (gnomAD): Loss-of-function variants: 31 observed, 57.89 expected, observed/expected ratio (o/e) 0.54, 90% interval 0.4 to 0.72. The upper end of that interval is the gene's LOEUF score, 0.72, which puts it in group 2 of 6, group 1 being the genes least tolerant of losing a copy. Missense variants: 652 observed, 750.34 expected, observed/expected ratio (o/e) 0.87, 90% interval 0.81 to 0.93. Synonymous variants: 262 observed, 296.99 expected, observed/expected ratio (o/e) 0.88, 90% interval 0.8 to 0.98.
Homologues: Orthologues: chimpanzee SYN3 (99% identical), macaque SYN3 (99% identical), dog SYN3 (94% identical), rabbit SYN3 (93% identical), mouse Syn3 (92% identical), rat Syn3 (92% identical), guinea pig SYN3 (86% identical), tropical clawed frog syn3 (72% identical), pig SYN3 (52% identical). Paralogues in human: SYN2 (59% identical), SYN1 (58% identical).
Diseases named in the same sentence as SYN3 in open-access papers:
SYN3 is named in the same sentence as 27 diseases in open-access papers, as found by Europe PMC text mining. Sharing a sentence is not in itself a finding about the gene and the disease. The quoted sentences say what the papers report.
schizophrenia (9 papers, 2006 to 2019). A major psychotic disorder characterized by abnormalities in the perception or expression of reality. "A nonsense mutation in the SYN1 gene was shown to cause familial epilepsy; and some studies have suggested an association of SYN3 with schizophrenia [Reviewed in:]." (PMID 27515700, 2016). "The synapsin III (SYN III) gene on chromosome 22q is a candidate gene for schizophrenia susceptibility due to its chromosome location, neurological function, expression patterns and functional polymorphisms." (PMID 19102774, 2008). "Three studies measured synapsin protein levels, and one found a significant reduction in synapsin III, while of the two studies quantifying mRNA, one found a significant reduction in synapsin II in schizophrenia." (PMID 29511299, 2019). "Since the human synapsin III gene is a potential locus for schizophrenia, we considered Syn3 as a candidate gene for Ofil2." (PMID 16768795, 2006). "SYN3 has a role in synaptogenesis and the modulation of neurotransmitter release, leading to its link to several neuropsychiatric conditions, including bipolar disorder, autism, schizophrenia and epilepsy." (PMID 29225348, 2017). "The synapsin III (SYN3) gene is located close to one of the multiple sclerosis susceptibility regions (in 22q13.1) and a candidate region implicated in linkage studies of schizophrenia." (PMID 24586301, 2014). "SYN3 (Homo sapiens synapsin III mRNA) encodes a neuronal phosphoprotein that is involved in synaptogenesis and in the modulation of neurotransmitter release, and it is implicated in several neuropsychiatric diseases such as schizophrenia." (PMID 18173853, 2008).
bladder cancer (3 papers, 2021 to 2025). "In respect to all these information, Kulkarni very recently elaborated the potential of rAd-IFN/Syn-3 to become the “New Gold Standard” for BCG-unresponsive bladder cancer patients." (PMID 34123841, 2021). "Preclinical studies of recombinant adenovirus expressing IFNα along with gene transfer enhancing agent Syn3 (rAd-IFNα/Syn3) demonstrated tumour regression of bladder cancer in murine models while achieving sustained high levels of IFNα in both urine and urothelium." (PMID 41300998, 2025). "Nadofaragene firadenovec (Ad-IFNα/Syn3) is now approved for BCG-unresponsive bladder cancer (BLCA)." (PMID 39559365, 2024). "Ad-IFNα/Syn3 is a non-replicating adenoviral vector that delivers a copy of the human IFNα2b transgene to bladder cancer and normal bladder urothelium, leading to the production of IFNα protein." (PMID 39559365, 2024).
Alzheimer disease (2 papers, 2022 to 2023). A progressive, neurodegenerative disease characterized by loss of function and death of nerve cells in several areas of the brain leading to loss of cognitive function such as memory and language. "The female-biased genes in four regions were enriched for Alzheimer’s disease progression (SYN3 and STK32B) and the male-biased genes in four brain regions were enriched for neuroticism (PAX6 and PLTP)." (PMID 37221602, 2023).
Anxiety (2 papers, 2017 to 2023). Intense feelings of nervousness, tension, or panic often arise in response to interpersonal stresses. "Many of the anxiety-related genes that contributed to these ontological terms have been previously implicated in psychiatric-related disorders, such as CUX2, SYN3, and JAG246,47." (PMID 29225348, 2017). "When considering NPDs of interest, depression, and anxiety alone, the strongest pleiotropic effects of single genes, i.e. highest number of associations with disorders, were observed for PFN2, HTRA1, SCRN1, ATAT1, and SYN3." (PMID 37461513, 2023).
Insulin resistance (2 papers, 2022 to 2023). Increased resistance towards insulin, that is, diminished effectiveness of insulin in reducing blood glucose levels. "Maternal indicators of insulin resistance and β-cell function in early pregnancy were associated with lower methylation at the CpG site cg03158092 located near the SYN3 gene and the CpG site cg05985988 located near the JARID2 gene, respectively." (PMID 36137169, 2022).
Parkinson disease (2 papers, 2020 to 2021). A progressive degenerative disorder of the central nervous system characterized by loss of dopamine producing neurons in the substantia nigra and the presence of Lewy bodies in the substantia nigra and locus coeruleus. "Synapsin III (SYN3) mainly involved in the development of brain or neurons disease, such as Parkinson disease, but the detailed relationship with ITP remains to be confirmed." (PMID 32258092, 2020).
age-related macular degeneration (1 paper, 2018). Age-related loss of vision in the central portion of the retina (macula), secondary to retinal degeneration. "Of note, SYN3/TIMP3 was also identified as susceptibility locus for age-related macular degeneration, a late-onset neurodegenerative disease of the retina involving amyloid-β pathology." (PMID 29860282, 2018).
Arthritis (1 paper, 2025). Inflammation of a joint. "Interestingly, in response to DMM injury, LG/J mice develop robust synovial and meniscal calcification, correlated with SNPs relating to angiogenesis, bone metabolism/calcification, arthritis, and ankylosing‐spondylitis and gene transcripts of Aff3, Fam81a, Syn3, and Ank." (PMID 39930949, 2025).
asthma (1 paper, 2025). "Additionally, genes involved in neurotransmitter signaling, such as SYN3 and PDE1A, indicate a potential neuro-immune connection in asthma and eczema." (PMID 41561239, 2025).
Atrophy (1 paper, 2015). Any weakening or degeneration, especially through lack of use. "There was a strong association between drusen area, volume and RPE atrophy in the macula with risk alleles in CFH (rs12038333) and SYN3 (rs5749482)." (PMID 25893111, 2015).
attention deficit and hyperactivity disorder (1 paper, 2022). "Synapsin III (Syn III) is a neuronal phosphoprotein regulating striatal dopaminergic neurotransmission in the adult brain and is involved in psychiatric disorders associated with dysfunctions of brain dopaminergic systems, including attention deficit and hyperactivity disorder (ADHD)." (PMID 36497160, 2022).
colon cancers (1 paper, 2022). "GGH, CACNG4, MME, SLC30A2, CKMT2, SYN3, and SLC22A31 were identified as differentially expressed both in glycolytic-cholesterogenic subgroups as well as between colon cancers and healthy samples, and were involved in glycolysis‒cholesterol synthesis." (PMID 36569910, 2022).
inflammatory bowel disease (1 paper, 2025). A spectrum of small and large bowel inflammatory diseases of unknown etiology. "SYN3 may influence gut function via neural signaling, affecting colonization by R. gnavus, which in turn alters carnitine metabolism, a pathway previously implicated in the pro-inflammatory landscape of inflammatory bowel disease." (PMID 41561239, 2025).
mood disorder (1 paper, 2016). A cognitive disorder a disturbance in which the person's mood is hypothesized to be the main underlying feature. "Synapsin genes – Synapsin I (SYN1), Synapsin II (SYN2), and Synapsin III (SYN3) – are interesting candidates for the etiology of mood disorders due to their involvement in the adult brain in synaptic transmission and plasticity, as well as in brain development in axon outgrowth and synaptogenesis." (PMID 27515700, 2016).
multiple sclerosis (1 paper, 2014). A progressive autoimmune disorder affecting the central nervous system resulting in demyelination. "The association of polymorphism of SYN3 with multiple sclerosis and several neuropsychiatric diseases have been reported." (PMID 24586301, 2014). "A number of studies have reported the association of the polymorphism of SYN3 with multiple sclerosis and several neuropsychiatric diseases." (PMID 24586301, 2014).
tauopathy (1 paper, 2023). Neurodegenerative disorders involving deposition of abnormal tau protein isoforms (tau proteins) in neurons and glial cells in the brain. "SYN3 itself is involved in neurotransmitter release and synaptogenesis, and has been shown to be downregulated in hippocampal CA1 neurons in a tauopathy mouse model." (PMID 38002954, 2023).
tumor (3 papers, 2014 to 2025). "CG0070 and rAd-IFN/Syn-3 are adenovirus-based vectors targeting the bladder tissue and lead to the production of anti-tumor cytokines upon transduction." (PMID 34123841, 2021). "Regression of GFP-labeled tumor cells was detected after 1h treatment to rAd-IFN/Syn-3, while no cytotoxic effect on normal tissue was observed." (PMID 34123841, 2021). "Intravesical instillation of IFN alone or the rAd-IFN without Syn3 showed no impact on tumor burden." (PMID 34123841, 2021).
movement disorder (1 paper, 2017). Neurological conditions resulting in abnormal voluntary or involuntary movement, which may impact the speed, fluency, quality and ease of movement. "A de novo double nucleotide substitution in SYN3 (c.1444_1445delinsTT; p.Pro481Leu), encoding synapsin III, was found in a proband with DD, seizures, atrophy of the cerebellar vermis, hypotonia, and a movement disorder." (PMID 28327206, 2017).
psychiatric disease (1 paper, 2015). "Of these SYN1, SYN2, and SYN3 are all associated with psychiatric disease, and the synaptic transmission and synaptic vesicle trafficking pathway." (PMID 26399914, 2015).
SYN3 also shares sentences with these, for which no sentence is quoted: bipolar disorder (2 papers); autism (1); benign meningioma (1); depression (1); diabetic retinopathy (1); eczema (1); epilepsy (1); ZIKV infection (1).